EML4 (EMAP like 4)
Description:
Essential for the formation and stability of microtubules (MTs). Required for the organization of the mitotic spindle and for the proper attachment of kinetochores to MTs. Promotes the recruitment of NUDC to the mitotic spindle for mitotic progression.
Synonyms: EMAP-4; C2orf2; EMAPL4; ROPP120; ELP120
Tractability: Small molecule: an approved drug acts on it; a high-quality ligand is known. PROTAC: ubiquitination databases record sites on it; its protein half-life has been measured; a small molecule that binds it is known. Other modalities: a drug acting on it is in phase 1 trials.
Chemical probes: ALECTINIB (high quality)
Gene: Protein-coding gene on chromosome 2 (42,169,330 to 42,332,548, forward strand). Ensembl gene ENSG00000143924.
Subcellular location: Cytoplasm, cytoskeleton; Cytoplasm; Cytoplasm, cytoskeleton, spindle; Cytoplasm, cytoskeleton, microtubule organizing center; Midbody
Subcellular location (Human Protein Atlas): Annulus; Microtubules; Primary cilium; Calyx; Cytokinetic bridge; Cytosol; Perinuclear theca; Principal piece
Pathways (Reactome):
Disease: ALK mutants bind TKIs; Signaling by ALK fusions and activated point mutants
Cell Cycle: EML4 and NUDC in mitotic spindle formation
Gene Ontology:
Molecular function: alpha-tubulin binding; beta-tubulin binding; protein binding; microtubule binding
Biological process: attachment of spindle microtubules to kinetochore; mitotic metaphase chromosome alignment; microtubule cytoskeleton organization; microtubule-based process; mitotic cell cycle
Cellular component: cytoplasm; cytosol; intercellular bridge; membrane; microtubule; microtubule cytoskeleton; microtubule organizing center; midbody; mitotic spindle; cytoskeleton; spindle
Genetic constraint (gnomAD): Loss-of-function variants: 48 observed, 89.79 expected, observed/expected ratio (o/e) 0.53, 90% interval 0.42 to 0.68. The synonymous counts are far from expectation, so gnomAD's model fits this gene poorly and the ratio says little. Missense variants: 1,082 observed, 968.33 expected, observed/expected ratio (o/e) 1.12, 90% interval 1.06 to 1.17. Synonymous variants: 409 observed, 339.17 expected, observed/expected ratio (o/e) 1.21, 90% interval 1.11 to 1.31.
Homologues: Orthologues: chimpanzee EML4 (99% identical), macaque EML4 (96% identical), dog EML4 (93% identical), pig EML4 (93% identical), rabbit EML4 (92% identical), guinea pig EML4 (90% identical), rat Eml4 (89% identical), mouse Eml4 (89% identical), tropical clawed frog eml4 (80% identical), zebrafish EML4 (72% identical). Paralogues in human: EML1 (45% identical), EML3 (45% identical), EML2 (38% identical), EML6 (31% identical), EML5 (31% identical), WDR90 (20% identical), CFAP44 (19% identical), CFAP251 (15% identical), CFAP52 (13% identical).
Diseases named in the same sentence as EML4 in open-access papers:
EML4 is named in the same sentence as 124 diseases in open-access papers, as found by Europe PMC text mining. Sharing a sentence is not in itself a finding about the gene and the disease. The quoted sentences say what the papers report.
lung cancer (309 papers, 2008 to 2026). A malignant neoplasm involving the lung. "The driver gene status of lung cancer, such as the echinoderm microtubule-associated protein-like 4 (EML4)-ALK fusion, highlights the heterogeneity of tumors at the molecular level." (PMID 40606995, 2025). "ALK gene abnormalities predominantly encompass fusions, point mutations, and amplifications, with EML4-ALK-positive non–small cell lung cancer representing a canonical example." (PMID 41614760, 2025). "In 1,076 formalin-fixed paraffin-embedded lung cancer samples, SplitFusion identified novel fusions and revealed that EML4::ALK variant 3 was associated with multiple fusion variants coexisting in the same tumor." (PMID 40041857, 2025). "Non-small cell lung cancer (NSCLC) is a type of lung cancer associated with translocation of the EML4 and ALK genes on the short arm of chromosome 2." (PMID 38319906, 2024). "Echinoderm microtubule-associated protein-like 4 (EML4)–anaplastic lymphoma kinase (ALK) oncogenic fusion proteins are found in approximately 5% of non–small cell lung cancers." (PMID 38458397, 2024). "EML4 (echinoderm microtubule-associated protein-like 4)-ALK in lung cancer is an example of a well-known gene fusion involving a kinase-coding gene." (PMID 39518064, 2024). "A CBRN ligand-based ALK PROTAC was shown to cause degradation of NPM-ALK and EML4-ALK in lung cancer lines at certain thresholds." (PMID 38835344, 2024). "Anaplastic lymphoma kinase (ALK) gene rearrangement in lung cancer was first reported as the echinoderm microtubule-associated protein-like 4 (EML4)-ALK fusion gene in adenocarcinoma." (PMID 39781173, 2024). "One of the most successful examples in lung cancer survival is seen in NSCLC patients harbouring the oncogenic fusion between echinoderm microtubule-associated protein-like 4 (EML4) and anaplastic lymphoma kinase (ALK)." (PMID 39695132, 2024). "These animal models are valuable as they exhibit sensitivity to ALK inhibition, allowing for the exploration of the mechanisms underlying EML4–ALK‐induced lung cancer and the evaluation of ALK‐targeted therapy's effectiveness." (PMID 38077251, 2023). "Similar results were observed in other cell lines ectopically expressing EML4-ALK variants and in EML4-ALK driven lung cancer cells." (PMID 38264745, 2023). "The EML4‐ALK fusion was shown to be variant 1 via comparative western blotting of the same variant harbored by the commonly used ALK‐rearranged lung cancer cell line NCI‐H3122." (PMID 36423211, 2023). "EML4-ALK lung cancers possess a low mutational burden and patients exhibit little or no response to anti-PD-1 checkpoint inhibitor therapy." (PMID 36739466, 2023). "All cell lines were isolated from C57BL/6 mice and express the mRNA encoding the EML4-ALK variant 1 fusion gene compared to KRAS-mutant murine LLC lung cancer cells." (PMID 36739466, 2023). "Genetic alterations of the PI3K, AKT, PTEN, EGFR, and KRAS genes, MET amplification, and EML4-ALK rearrangements are associated with lung cancer progression." (PMID 36230484, 2022). "EML4 is currently receiving attention due to its possible fusion with anaplastic lymphoma kinase (ALK) forming pathological EML4-ALK variants associated with lung cancer." (PMID 35478957, 2022). "Specifically, we identified three lung cancer patients with EML4-ALK, who each also harbored an activating mutation in KRAS, and loss of function mutations in BRCA2 and PTEN, respectively." (PMID 36369474, 2022). "The EML4-ALK fusion was first detected in a Japanese patient with lung cancer, and this fusion mutation was mutually exclusive with oncogenic driver mutation types such as KRAS or EGFR." (PMID 36591504, 2022). "The EML4-ALK fusion was first observed in five out of 75 (6.7%) Japanese patients with lung cancer, occurring mutually exclusive of other driver mutations such as EGFR or KRAS." (PMID 33806977, 2021).
lung cancer (continued). "In cancers driven by ALK fusions such as EML4(Echinoderm microtubule-associated protein-like 4)-ALK(+) lung cancer, ALKi+RAFi+MEKi+ERKi treatment was very effective in suppressing tumor cell growth." (PMID 34461089, 2021). "The most common EML4-ALK variants are variants 1 and 3, which account for about 60% of EML4-ALK-positive lung cancer cases." (PMID 34090412, 2021). "Echinoderm microtubule-associated protein-like 4 – anaplastic lymphoma kinase (EML4-ALK) gene fusions are prevalent in lung cancer and treatment with ALK inhibitors is a part of conventional care." (PMID 33878728, 2021). "These associations include APC/CDC20 for EML4-ALK fusions in lung cancers, SPOP for NUP98-NSD1 and BCR-ABL fusions in LAML, and FBW7 (or FBXW7, F-box and WD repeat domain containing 7) for CCDC6-RET fusions in thyroid carcinomas (THCAs)." (PMID 34795215, 2021). "One of the first oncogenic drivers to be reported in lung cancer was the fusion of echinoderm microtubule-associated protein-like 4 (EML4) and anaplastic lymphoma kinase (ALK) (EML4-ALK) in 2007." (PMID 32640547, 2020). "Last, two lung function variants mapped to genes somatically mutated in lung cancer: EML4 (rs12466981: PFEV1/FVC = 2.7 × 10−14) and BRAF (rs13227429: PFVC = 5.6 × 10−9)." (PMID 31911640, 2020). "Fusion genes play a major role in the pathogenesis of lung cancers, and the discovery of microtubule-associated protein-like 4–anaplastic lymphoma kinase (EML4–ALK) fusion kinase in 2007 which is a breakthrough in targeted treatment for lung cancer." (PMID 32587276, 2020). "Patients with non‐small cell lung cancer (NSCLC) harboring the echinoderm microtubule‐associated protein‐like 4 (EML4)–ALK fusion exhibit remarkable initial responses to ALK‐TKIs." (PMID 31633304, 2019). "The fusion between echinoderm microtubule-associated protein-like 4 (EML4) gene and ALK (EML4-ALK) was the first fusion oncogene detected in lung cancer." (PMID 31795465, 2019). "EGFR mutation, KRAS mutation, and EML4-ALK in lung cancer case were commonly annotated resistance information by OKR and QCII." (PMID 31383922, 2019). "EGFR mutation and EML4-ALK fusion gene for lung cancer were common variants described in three systems with the same evidence levels (level I)." (PMID 31383922, 2019). "The echinoderm microtubule-associated protein-like 4 (EML4)-ALK fusion protein was the first reported oncogenic kinase in lung cancer and is located on chromosome 2." (PMID 29435193, 2018). "Fusion-circRNA (F-circRNA) can be used as a diagnostic marker for the echinoderm microtubule-associated protein-like 4 (EML4)/anaplastic lymphoma kinase (ALK1) gene fusion mutation in lung cancer." (PMID 30400981, 2018). "With regards to lung cancer, the H2228 and H3122 human lung cancer cell lines are EML4-ALK-positive (though they carry different variants) and have been widely used to dissect ALK signaling." (PMID 29455675, 2018). "Patients with Echinoderm microtubule-associated protein-like 4 (EML4)-anaplastic lymphoma kinase (ALK) positive lung cancer are sensitive to ALK-kinase inhibitors." (PMID 29304828, 2018). "Though harbored by only 4–6% of lung adenocarcinomas, EML4-ALK fusion has been recognized as the second most important event to consider in the targeted treatment of lung cancer, following the EGFR mutation." (PMID 28535796, 2017). "Among the most abundant are fusions of the ALK gene with portions of the gene encoding the echinoderm microtubule-associated protein-like 4 (EML4) in lung cancer." (PMID 29189709, 2017). "EML4-ALK-positive lung cancer is common among adenocarcinomas and is associated with an acinar-type histology and sieve-like structure and/or signet ring cells with abundant mucin growing in solid sheets." (PMID 26964537, 2016).
lung cancer (continued). "Recently, activation of the anaplastic lymphoma kinase (ALK) gene in lung cancer by fusion to echinoderm microtubule-associated protein-like 4 (EML4) or other gene partners (such as BIRC6, TFG, KIF5B and KLC1) has been identified as oncogenic events." (PMID 26789109, 2016). "Echinoderm microtubule-associated protein-like 4-anaplastic lymphoma kinase (EML4-ALK)-positive lung cancer presenting with Ground-glass nodules (GGNs) is relatively rare, and few such cases have been reported." (PMID 26964537, 2016). "Echinoderm microtubule associated protein like 4 anaplastic lymphoma kinase (EML4-ALK) as a new biological marker is a hot topic in the field of lung cancer treatment." (PMID 25676402, 2015). "The discovery of an echinoderm microtubule-associated protein-like 4 (EML4)-anaplastic lymphoma kinase (ALK) fusion gene led to improved clinical outcomes in patients with lung cancer after the development of the first ALK-targeting agent, crizotinib." (PMID 25941796, 2015). "It was reported that EML4-ALK variant 1 (EAV1) has the highest frequency in patient with EML4-ALK+ lung cancer." (PMID 26517679, 2015). "In the year 2007, the fusion of echinoderm microtubule-associated protein-like 4 (EML4) genes with anaplastic lymphoma kinase (ALK) was found in lung cancer." (PMID 25706305, 2015). "It was recently reported that genomic translocation in lung cancer was observed and that the echinoderm microtubule-associated protein-like 4-anaplastic lymphoma kinase (EML4-ALK) fusion gene plays an important role in lung cancer." (PMID 25097864, 2014). "EML4-ALK mutations in lung cancer that confer resistance to ALK inhibitors ALK Lung Cancer Study Group." (PMID 25628210, 2014). "The presence of an EML4-ALK translocation with concomitant EGFR/KRAS mutations is very rare among lung cancer patients." (PMID 23341890, 2013). "Similar to EGFR mutations in lung cancer, EML4-ALK mutations occur primarily in the adenocarcinoma subtype, and usually occur in never- and light-smokers." (PMID 22928112, 2012). "Over ten EML4-ALK variants have been identified in lung cancer so far, as well as other fusion partners TFG and KIF5B." (PMID 22825000, 2012). "Among the 23 lung cancer-associated genes, gene fusions were detected in 2 samples: one with EML4-ALK fusion and another with ALK-unknown gene fusion." (PMID 40948762, 2025). "Using an in vitro drug screening approach, we found that ESK440 significantly inhibits proliferation of cancer cells with different types of ALK genomic aberrations such as lung cancer cells (EML4-ALK fusion) and NB cells (mutations, amplifications), as well as some of the DIPG cells." (PMID 39900433, 2025). "Increasing evidence suggests that lung cancer patients with EML4::ALK v3 tumors may have less favorable clinical outcomes compared to patients with other EML4::ALK variants." (PMID 40041857, 2025). "Anaplastic lymphoma kinase (ALK) can be driven to oncogenic activity by different types of mutational events such as point‐mutations, for example F1174L in neuroblastoma, and gene fusions, for example with echinoderm microtubule‐associated protein‐like 4 (EML4) in non‐small cell lung cancer (NSCLC)." (PMID 37149843, 2023). "We designed in vitro experiments in this study to reduce and eliminate residual cancer cells maintained by treatment-induced adaptive reprogramming using three ALK-rearranged lung cancer cell lines with different EML4-ALK variants (H3122, H2228, and A925L cells)." (PMID 35228642, 2022). "Consistently, in NPM-ALK+ ALCL, as in EML4-ALK lung cancers and ALK-mutated neuroblastoma, a synergistic activity of ALK and mTOR inhibition had been described, although the authors did not investigate the involvement of autophagy associated with cell death in these settings." (PMID 33066037, 2020).
lung cancer (continued). "Lung cancer-associated EML4/ALK1 translocation also gives rise to F-circRNA, which may play an important role in the development and progression of lung cancers and serve as a novel entry point for the diagnosis of lung cancer." (PMID 30400981, 2018). "Another reasonably common mutation identified in two landmark studies in 2007 was the first somatic oncogenic gene translocation in lung cancer, involving fusion of two genes, EML4 (echinoderm microtubule associated protein-like 4) and ALK (anaplastic lymphoma kinase)." (PMID 26755435, 2016). "Previous reports showed twelve cases of EML4–ALK-positive lung cancer with EGFR mutation." (PMID 23714228, 2013). "Perhaps the most striking recent improvements in lung cancer survival are seen among patients whose cancers are driven by a distinctive molecular event, the fusion between echinoderm microtubule‐associated protein‐like 4 (EML4) and anaplastic lymphoma kinase (ALK)." (PMID 37149843, 2023). "Molecular analysis is commonly used in samples obtained by EBUS-TBNA from patients with lung cancer, where they have been used to distinguish different types of non-small-cell lung cancer and to detect epidermal growth factor mutations and the EML4-ALK fusion gene." (PMID 23196318, 2013). "EML4-ALK-positive lung cancer represents an important molecular subtype of non-small-cell lung cancer (NSCLC) that initially responds to ALK inhibitors but invariably develops resistance, highlighting the need for novel targeted therapeutic strategies." (PMID 42280172, 2026). "Subsequently, next-generation sequencing involving 68 lung cancer-related genes identified an EML4 (exon 6):: ALK (exon 20) gene fusion(V3)." (PMID 40224190, 2025). "The combination of Vincristine and Crizotinib inhibits tumor cell proliferation and blocks the RAS/MAPK, PI3K/AKT, and JAK/STAT3 signaling pathways in nonsmall cell lung cancer EML4-ALK V1 cells." (PMID 40662801, 2025). "Exosomal RNA has been shown to carry oncogenic transcripts, like EGFRvIII in glioblastoma, and fusion RNAs, such as EML4-ALK in lung cancer." (PMID 41020861, 2025). "Together, these results provide strong evidence that CAFs establish a protective niche for EML4-ALK-rearranged lung cancer cells toward ALK inhibition." (PMID 40524253, 2025). "Regarding genetics, among the 3 common lung cancer gene variants (EGFR mutation, KRAS mutation, and EML4/ALK rearrangement), EML4/ALK rearrangement is considered to be a high-risk factor for the development of PE." (PMID 39754212, 2025). "The EML4‐ALK fusion is the most common ALK rearrangement in non‐small cell lung cancer, and multiple ALK tyrosine kinase inhibitors have been approved." (PMID 40904239, 2025). "Next, mice subcutaneously injected with H1299 control (without RNase1 expression), RDAA (ALK and RNase1 co-expression), or ALK mut lung cancer cells (EML4-ALK expression) were treated with ceritinib for two weeks (25 mg/kg/day)." (PMID 40246819, 2025). "ALK gene fusions have been reported frequently in lung cancer, especially in non-small-cell lung cancer, and EML4-ALK is known to be the most frequent driver gene." (PMID 40647546, 2025). "In this study, reversible resistant state was induced by alectinib in EML4-ALK mutant lung cancer cell." (PMID 40234387, 2025). "Studies suggest that platelets from lung cancer patients can carry fusion transcripts from tumor cells, and monitoring EML4-ALK rearrangement fusion transcripts can predict the therapeutic response to ALK inhibitors in lung cancer patients." (PMID 38561776, 2024). "In summary, we have uncovered that EML4-ALK fusion protein in lung cancer cells enhances venous thrombogenicity through the pERK1/2-AP-1-tissue factor axis." (PMID 37940761, 2024). "In lung cancers, the most common rearrangement involves the fusion of the ALK gene with EML4 (echinoderm microtubule-associated protein-like 4)." (PMID 39199653, 2024).